ADGRV1 (adhesion G protein-coupled receptor V1)
Diseases named in the same sentence as ADGRV1 in open-access papers (continued):
Sharing a sentence is not in itself a finding about the gene and the disease.
retinopathy (3 papers, 2021 to 2025). "The present study thus provides the first comprehensive overview of ADGRV1 retinopathy." (PMID 34638692, 2021). "ADGRV1 and USH2A retinopathy share all the major characteristics of functional and structural impairment, suggesting that the loss of function of the corresponding proteins produces similar effects in the retina." (PMID 34638692, 2021). "ADGRV1 and USH2A retinopathy produce indistinguishable clinical profiles, suggesting that their loss of function produces similar effects in the retina." (PMID 37628652, 2023). "ADGRV1 and USH2A retinopathy were indistinguishable in all major functional and structural characteristics, suggesting that the loss of function of the corresponding proteins produces similar effects in the retina." (PMID 34638692, 2021).
ADGRV1 also shares sentences with these, for which no sentence is quoted: myoclonic epilepsy (5 papers); Hearing impairment (4); hepatocellular carcinoma (3); Usher syndrome type 1 (3); autosomal recessive deafness 31 (2); colorectal cancer (2); generalized epilepsy (2); glioblastoma (2); muscular dystrophy (2); nervous system disorder (2); nyctalopia (2); retinal dystrophies (2); schizophrenia (2); Sensory hearing loss (2); tumor (2); acute lymphoblastic leukemia (1); Alstrom syndrome (1); Alzheimer disease (1); Arts syndrome (1); Atrophy (1); Blindness (1); brain arteriovenous malformation (1); cardiac conduction disorder (1); childhood absence epilepsy (1); congenital heart anomalies (1); convulsion (1); developmental delay (1); Dravet syndrome (1); encephalitis (1); endolymphatic hydrops (1).
A further 31 diseases each share a sentence with ADGRV1 in 1 paper.